SACK1D (scaffolding CK1 anchoring protein D)
Description:
Through the degradation of FBXW7, may act indirectly on the expression and downstream signaling of MTOR, JUN and MYC. May play also a role in cell proliferation through activation of the ERK1/ERK2 signaling cascade. May also be important for proper chromosome congression and alignment during mitosis through its interaction with KIF22.
Synonyms: FAM83D; C20orf129; dJ616B8.3; CHICA
Tractability: PROTAC: ubiquitination databases record sites on it.
Gene: Protein-coding gene on chromosome 20 (38,926,312 to 38,953,106, forward strand). Ensembl gene ENSG00000101447.
Subcellular location: Cytoplasm; Cytoplasm, cytoskeleton, spindle; Cytoplasm, cytoskeleton, spindle pole
Subcellular location (Human Protein Atlas): Mitotic spindle; Cytokinetic bridge; Cytosol; Microtubules
Pathways (Reactome):
Signal Transduction: Signaling by EGFR
Gene Ontology:
Molecular function: kinesin binding; microtubule binding; protein binding; protein kinase binding
Biological process: cell migration; cell population proliferation; epithelial to mesenchymal transition; metaphase chromosome alignment; positive regulation of cell cycle G1/S phase transition; protein localization to mitotic spindle; regulation of ERK1 and ERK2 cascade; regulation of protein catabolic process; regulation of TOR signaling; signal transduction
Cellular component: cytoplasm; cytosol; microtubule cytoskeleton; mitotic spindle; mitotic spindle pole; spindle; spindle pole
Genetic constraint (gnomAD): Loss-of-function variants: 26 observed, 20.65 expected, observed/expected ratio (o/e) 1.26, 90% interval 0.92 to 1.73. The upper end of that interval is the gene's LOEUF score, 1.73, which puts it in group 6 of 6, group 1 being the genes least tolerant of losing a copy. Missense variants: 740 observed, 720.06 expected, observed/expected ratio (o/e) 1.03, 90% interval 0.97 to 1.09. Synonymous variants: 310 observed, 295.95 expected, observed/expected ratio (o/e) 1.05, 90% interval 0.95 to 1.15.
Homologues: Orthologues: chimpanzee FAM83D (99% identical), guinea pig FAM83D (81% identical), pig FAM83D (79% identical), dog FAM83D (79% identical), rat Fam83d (78% identical), mouse Fam83d (77% identical), tropical clawed frog fam83d (47% identical), zebrafish fam83d (36% identical). Paralogues in human: SACK1G (25% identical), SACK1H (24% identical), SACK1B (24% identical), SACK1C (23% identical), SACK1E (23% identical), SACK1F (22% identical), SACK1A (19% identical).
Diseases named in the same sentence as SACK1D in open-access papers:
SACK1D is named in the same sentence as 52 diseases in open-access papers, as found by Europe PMC text mining. Sharing a sentence is not in itself a finding about the gene and the disease. The quoted sentences say what the papers report.
Palmoplantar keratoderma (1 paper, 2026). Abnormal thickening of the skin of the palms of the hands and the soles of the feet. "In cells derived from palmoplantar keratoderma patients harboring the CK1α-binding-deficient SACK1GR265P mutation, DEG-77 targets CK1α and mitotic SACK1D but not SACK1GR265P, highlighting the requirement for CK1α-SACK1 interaction to achieve codegradation." (PMID 41955445, 2026).
SACK1D also shares sentences with these, for which no sentence is quoted: tumor (37 papers); cancer (34); breast carcinoma (17); hepatocellular carcinoma (16); ovarian carcinoma (12); colorectal cancer (10); gastric cancer (8); lung adenocarcinoma (7); lung carcinoma (5); non-small cell lung carcinoma (5); esophageal cancer (4); triple-negative breast carcinoma (4); glioma (3); liver cancer (3); gastric tumor (2); glioblastoma (2); lung squamous cell carcinoma (2); lymph node metastasis (2); pancreatic adenocarcinoma (2); sarcoma (2); adrenocortical carcinoma (1); alcohol (1); asthma (1); breast tumors (1); cervical cancer (1); cholangiocarcinoma (1); colon adenocarcinoma (1); colon cancer (1); endometrial cancer (1); Fanconi anemia (1).
A further 21 diseases each share a sentence with SACK1D in 1 paper.